LGALS7 (galectin 7)
Diseases named in the same sentence as LGALS7 in open-access papers (continued):
Sharing a sentence is not in itself a finding about the gene and the disease.
cancer (continued). "Intracellular galectin-7 is recognized as a multifunctional protein involved in processes such as cell proliferation, apoptosis, and cell migration, and galectin-7 also serves as a marker of cancer metastasis." (PMID 33425778, 2020). "Consequently, galectin-7 appears as a useful therapeutic tool to regulate AJ dynamics and delay cancer progression." (PMID 29213102, 2017). "Paradoxically, galectin-7 may also induce the expression of genes known to promote cancer progression, including matrix metalloproteinase-9 (MMP-9) 27,28." (PMID 24515895, 2014). "To further determine the importance of DNA methylation in the regulation of galectin-7 gene expression in various tumor cells, we treated 26 cancer cell lines from five different organ origins with 50 nmol/L 5-Aza-dC and performed RT-PCR analysis and real-time RT-PCR analysis." (PMID 23985992, 2013). "The test region of galectin-7 was hypermethylated in these cancer cell lines." (PMID 23985992, 2013). "Therefore, the precise role of galectin-7 in cancer development is still debated and appears to be tissue specific, which we find fascinating." (PMID 23985992, 2013). "Consequently galectin-7 has shown major roles in cancer development, by helping either in the elimination of certain tumour types or in the growth stimulation of others." (PMID 22059385, 2012). "Growing evidence indicates that galectin-7 plays an important role in cancer progression." (PMID 20546628, 2010). "There are several reports of galectin-7 expression in human cancers." (PMID 20546628, 2010). "Besides, some reports showed that galectin-7 expression altered during the tumour progression in some kinds of carcinomas." (PMID 20546628, 2010). "LGALS7 is one of fifteen members of the B-galactoside-binding lectin family, some of which have been shown to influence cell growth, cell cycle, apoptosis and cell migration via their predicted role in homeostasis, however, the role of LGALS7 in cancer is unclear." (PMID 17543121, 2007). "Therefore, galectin-7 is considered a mediator of tumor metastasis and could be a potential target of cancer immunotherapy." (PMID 39465762, 2024). "Moreover, cancer treatments can enhance galectin 7 expression." (PMID 38503797, 2024). "Although several strategies were developed to knockout galectin-7 or suppress its translation, we believe the field of cellular pathophysiology would benefit from small-molecule inhibitors which can be administered to evaluate its effect on cellular disorders and even diseases such as cancer." (PMID 34827718, 2021). "This apparent inconsistency could reflect localization heterogeneity and functional implication of galectin-7 as it had primarily nuclear localization in normal cells, whereas it was detected ubiquitously in the cytoplasm, nuclei, and membranes of cancer cells." (PMID 32731422, 2020). "Indeed, galectin-7 has been proposed to serve as a marker in patients with certain type of cancer." (PMID 29257082, 2017). "Interestingly, galectin-7 overexpression on tumour tissues could be correlated to patient survival notably in ovarian or in cervical carcinomas." (PMID 29257082, 2017).
cancer (continued). "However, very little is known about how galectin-7 expression affects cancer progression." (PMID 24515895, 2014). "Interestingly, galectin-7 may contribute to the suppression of cancer proliferation in certain tumor types and induce the growth and metastasis of others." (PMID 23985992, 2013). "In addition, there are several reports of a role of galectin-7 in cancer development." (PMID 23985992, 2013). "However, the role of galectin-7 in cancer tumorigenesis remains unclear because there are several conflicting reports of galectin-7 function." (PMID 23985992, 2013). "In addition to its physiological function, galectin 7 may play a role in cancer." (PMID 38503797, 2024). "In cutaneous SCC, that originates from keratinocytes in the skin, we observed the expression of galectin-7 genes (LGALS7 and LGALS7B) in both normal and cancer cells." (PMID 38384845, 2024). "In addition, galectin-7 may have a protective effect on cancer, depending on the tissue type." (PMID 34827718, 2021). "The relationship between Tid1 and cancer progression has been extensively investigated in studies of HER2, c-Met receptor tyrosine kinase (MetR), signal transducer and activator of transcription 5 b (STAT5b), Akt, adenomatous polyposis coli, and galectin-7." (PMID 33233689, 2020). "One mechanism of the pro-tumor role of galectin-7 may involve induction of MMP-9, which plays an important role in cancer progression and metastasis." (PMID 20546628, 2010). "We also demonstrated that knockdown of Tid1 might contribute to cancer progression via the galectin-7-MMP-9 pathway, but not via mitochondrial dysfunction, ROS, EMT, and IL-8." (PMID 33233689, 2020). "Adjacent non-malignant tissues exhibited absent or markedly weaker expression for Galectin-4, Galectin-7, MUC21, ST6GALNAC1, and ST6GALNAC2 compared to the corresponding cancer tissues." (PMID 40718829, 2025).
tumor (37 papers, 2010 to 2026). "Up-regulation of LGALS7 expression has been linked to activation of multiple transcriptional programs involved in tumor survival, metabolism and inflammatory responses." (PMID 36693903, 2023). "It is possible that the uncontrolled growth of these galectin-7-expressing cells causes the increase in galectin-7 in the serum as a byproduct of having more galectin-7 production by the tumor." (PMID 34638303, 2021). "On the contrary, using inhibitors of galectin-7 has to be tested in tumours where its expression is associated with pejorative prognosis." (PMID 29257082, 2017). "The anti-tumor roles of galectin-7 are associated with induction of apoptosis or inhibition of cell proliferation." (PMID 20546628, 2010). "In addition, de novo galectin-7 expression was associated with progression to high-grade tumours and was enriched in metastatic samples compare to low-grade tumours." (PMID 29257082, 2017). "Interestingly, galectin-7 is detected in tumor-associated macrophages." (PMID 34572756, 2021). "Preoperative serum levels of osteopontin, galectin-7, and established tumor markers (CA-125, CA19-9, CA15-3, CEA, AFP) were analyzed." (PMID 41899101, 2026). "The tumor suppressive effect of galectin 7 is dependent on the function of the immune system, as the overexpression of mouse galectin 7 in the LL/2 cell line enhanced tumor growth in NSG mice, unlike WT mice." (PMID 38503797, 2024). "Combined with results from syngeneic mouse tumor models, these findings suggest that galectin 7 can impact tumor immune response with potential clinical impact." (PMID 38503797, 2024). "Overall, these correlations are consistent with the results from mouse tumor models which showed reduction in CD4+ T cells upon galectin 7 injection or overexpression." (PMID 38503797, 2024). "For example, in tumors with reduced infiltration of regulatory T cells, galectin 7 can be less effective in restoring anti-tumor immune response and even enhance tumor cell growth, as observed in the NSG mouse model." (PMID 38503797, 2024). "We then tested the significance of galectin 7 activity on T cells in vivo using a syngeneic tumor model." (PMID 38503797, 2024). "Accordingly, analysis of tumor dLNs revealed a significantly higher percentage of M-MDSC, reduced frequency of PMN-MDSC and higher M-MDSC/PMN-MDSC ratio in tumor-bearing Tg46 mice compared with WT or Lgals7−/− mice." (PMID 36693903, 2023). "Upregulation of galectin-7 was sufficient to induce a metastatic feature of tumor cells and rendered them resistant to cell death." (PMID 36873388, 2023). "At day 60, almost 80% of Tg46 animals developed at least one tumor, compared to 50% of WT and 25% of Lgals7−/− mice, with a considerably higher number of tumors per animal from day 80 onwards." (PMID 36693903, 2023). "In gastric cancer, there was significant statistical correlation between low levels of galectin-7 in tumor tissues compared with corresponding normal tissues." (PMID 37305017, 2022). "Like many galectins, galectin-7 displays opposite effects in terms of tumor progression from one histological type to another." (PMID 34827718, 2021). "The staining of galectin-7 in tumor cells was mainly observed in the cytoplasm; only a few individual cases showed nuclear staining." (PMID 34827718, 2021). "Such a role for galectin-7 in the tumor microenvironment would include its ability to induce local immunosuppression, as we know now that galectin-7, like many galectins, induces apoptosis in activated immune cells." (PMID 34198494, 2021). "Today, when studying the role of galectin-7 in tumor progression, most notably during metastasis, it is difficult to ignore the relationship of galectin-7 with MMP-9." (PMID 34198494, 2021).
tumor (continued). "Galectin-7 is believed to have a significant impact on tumor progression by inducing immunosuppression and increasing the invasive behavior of tumor cells that eventually leads to metastasis." (PMID 34827718, 2021). "In vitro as well as in vivo studies had indicated tumor suppressive effect of galectin-7 on colon cancer." (PMID 29854732, 2018). "Regarding tumour biology, galectin-7 downregulation correlates with poor tumour differentiation in bladder squamous cell carcinomas and in vulvar squamous cell carcinoma." (PMID 29257082, 2017). "As the pictures presented, the expression of galectin-7 dominantly presented in cytoplasm and nuclear of tumor cells and the expression level varied in patient specimens." (PMID 27259255, 2016). "Galectin-7, has a controversial role in tumor progression, can either suppress tumor growth or induce chemoresistance depends on different tumor histology types." (PMID 27259255, 2016). "In conclusion, our study galectin-7 expression in tumor tissue as a potential independent predictive factor for OS in patients with non-metastasis ccRCC." (PMID 27259255, 2016). "Alternatively, galectin-7 mediates the nuclear export of Smad3 through complex formation, which is essential for the tumor-suppressive effects of hepatocyte growth factor on the transforming growth factor-beta signaling pathway." (PMID 24515895, 2014). "This study suggests that low galectin-7 protein expression translates into low cumulative survival rate in patients with OSCC via tumor resistance to preoperative chemotherapy and/or radiotherapy." (PMID 24515895, 2014). "In conclusion, we identified galectin-7 as a predictor of tumor resistance and developed a predictive formula for patient survival." (PMID 24515895, 2014). "Expression of galectin-7 is positively altered in certain tumours that exhibit an aggressive phenotype." (PMID 26269723, 2014). "The expression level of galectin-7 varies widely among tumor types, from completely downregulated to highly upregulated 21–24." (PMID 24515895, 2014). "Like other members of the galectin family, galectin-7 has been shown to either positively or negatively modulate apoptosis and tumor growth." (PMID 23658821, 2013). "It thus seems that galectin-7 can act either as a positive or as a negative regulatory factor in tumor development, depending on the histological type of the tumor." (PMID 23530091, 2013). "Altered galectin-7 expression is involved in tumor progression through the regulation of cell proliferation, apoptosis induction, and cell invasion." (PMID 23985992, 2013). "While galectin-7 negatively regulates some tumor types, it can stimulate the growth and/or development of others." (PMID 23530091, 2013). "Other family members, including Galectin-7 and Galectin-8, display context-dependent functions that may either promote or inhibit tumor development." (PMID 42129932, 2026). "Hence, PANC754 with its RBP/histone repression complex suppresses LGALS7 level can improve the recognition and phagocytosis of the tumor cells by NKs and CTLs." (PMID 40634299, 2025). "Immune-related genes, such as chemokine (Cxcr2), C-type lectin (Clec4e), chemokine ligand (Cxcl3), tumor growth-related genes, galectin-7 (Lgals7), and matrix metallopeptidase 8 (Mmp8), were downregulated by colonization of B. plebeius in colon tissues of the mice exposed to AOM/DSS." (PMID 39804065, 2025). "In brief, METTL3-modificatory m6A regulates the interaction of PANC754 with PSPC1 and H3K4me1 to form ncRNA/RBP/histone repression complex at gene promoter region to mediate the “Don’t eat me” LGALS7 signaling pathway, thereby exerting tumor-suppressing effects against CRC." (PMID 40634299, 2025). "Overexpression of galectin 7 suppressed tumor growth in the anti-mPD-1 antibody co-injection group." (PMID 38503797, 2024). "Galectin-7 has been shown to be an important mediator in various tumor entities." (PMID 39465762, 2024). "During tumor progression, galectin-7 is released extracellularly." (PMID 39465762, 2024).
tumor (continued). "Transfection of T-cell lymphoma cells with galectin-7 also increases tumor growth in mice." (PMID 36873388, 2023). "Furthermore, splenic M-MDSCs isolated from tumor-bearing Tg46 mice showed increased T-cell inhibitory activity, as compared with those from WT or Lgals7−/− mice." (PMID 36693903, 2023). "Galectin-7 has a reverse effect on tumor growth and progression." (PMID 37305017, 2022). "In the tumor cell model with high galectin-7 expression, the number of T cells was found to significantly decrease, which cemented the hypothesis that galectin-7 could directly induce T cell apoptosis." (PMID 36428567, 2022). "These macrophages might also provide a source of extracellular galectin-7 for tumor cells and might regulate the intracellular galectin-7 pool." (PMID 34827718, 2021). "First, galectin-7 is not always associated with apoptosis and is often, if not most of the time, associated with tumor progression." (PMID 34198494, 2021). "In a recent article, St-Pierre and colleagues demonstrated that recombinant galectin-7 added on tumour cells may rapidly traffic through intracellular compartments including endocytic vesicle and mitochondria and could induce ectopic expression of galectin-7." (PMID 29257082, 2017). "Administration of pure recombinant galectin-7 could be efficient in immunosuppressive approaches targeting T lymphocytes but contrastingly it could enhance invasive potential of tumour cells." (PMID 29257082, 2017). "This is particularly important regarding the biomedical field because galectin-7 could influence tumour progression." (PMID 29257082, 2017). "We conducted multivariate Cox regression analysis to apprise the independent prognostic power of galectin-7 and all accessible clinic-pathologic variables (tumor size, pathological T-stage, necrosis, Fuhrman grade, sarcomatoid, LVI and ECOG-PS) in non-metastasis ccRCC." (PMID 27259255, 2016). "Galectin-7 showed increased levels in OSCC tumours as well as in saliva samples." (PMID 26269723, 2014). "Because overexpression of galectin-7 is known to regulate tumor growth and metastasis in multiple tumor cell types, we next investigated whether galectin-7 could modulate the growth of primary tumors and the dissemination of metastasis." (PMID 23658821, 2013). "Whether macrophages produce galectin-7 themselves or take it up from neighbor tumor cells remains unknown, nor is the functional impact of galectin-7 on tumor-associated macrophages." (PMID 34572756, 2021). "In addition, galectin-7 was also present in macrophages next to the tumor cells." (PMID 34827718, 2021). "Although our research emphasized that PANC754 downregulates the level of the “Don’t eat me” signal LGALS7 to improve the immune efficiency of ICB and induce NK or CTL cells to release Perforin and cytokines to kill tumor cells." (PMID 40634299, 2025). "We report that galectin 7 reduced CD4+ T cell percentage in both in vitro culture and mouse tumor models." (PMID 38503797, 2024). "Fifteen days after tumor cell injection, the mice were treated with vehicle (PBS) or galectin 7 (1.5 mg/kg) every 4 days." (PMID 38503797, 2024). "In this study, the injection of galectin 7 reduced CD4+ T cells and suppressed tumor growth in the MC38 syngeneic mouse tumor model using WT mice but not in PD-1 KO mice." (PMID 38503797, 2024). "As the results presented, tumor size, pathological T stage, necrosis, sarcomatoid, LVI and galectin-7 were independently predictive factors of OS, while Fuhrman grade and showed no significance.." (PMID 27259255, 2016).